IL4 (interleukin 4)
Diseases named in the same sentence as IL4 in open-access papers (continued):
Sharing a sentence is not in itself a finding about the gene and the disease.
pneumonia (43 papers, 2009 to 2025). An acute, acute and chronic, or chronic inflammation focally or diffusely affecting the lung parenchyma, caused by an infection in one or both of the lungs (by bacteria, viruses, fungi, or mycoplasma.). "The observed changes in the content of CD4+FoxP3+ lymphocytes in acute pneumonia suggests a possible association with the activity of anti-inflammatory cytokines, primarily interleukin-4." (PMID 41463029, 2025). "However, IL-4 is shown to be associated with the remodeling of lung tissue in the late stages of pneumonia, whereas our patients were recruited in the study on earlier stages of disease." (PMID 36430621, 2022). "The obtained data on T-lymphocytes dynamics in acute pneumonia provide the basis for further analysis of the relationship of these cells with the cytokine profile, particularly IL-4 and TGF-β levels." (PMID 41463029, 2025). "This vaccine elicited IL-17 and IL-4 secretion by T cells, enhancing mucosal immunity when administered IN and providing protection against lethal pneumonia." (PMID 40076637, 2025). "An increase in IL-4 levels in the treatment of acute pneumonia indicates activation of the anti-inflammatory immune response and a possible strengthening of regulatory mechanisms." (PMID 41463029, 2025). "In acute pneumonia, the concentration of IL-4 in the blood serum increased significantly compared with the control." (PMID 41463029, 2025). "Compared with the HMPV pneumonia group and healthy control group, the former had a significantly lower level of IL-2 and higher levels of IL-4, IL-6, IL-10, and IFN-γ." (PMID 36496397, 2022). "When compared with the healthy children, children who were infected with HMPV pneumonia had a significantly lower level of IL-2 (p < 0.001) and higher levels of IL-4 (p < 0.001), IL-6 (p = 0.001), IL-10 (p < 0.001), and IFN-γ (p < 0.001)." (PMID 36496397, 2022). "The present study demonstrates that the Feishu point exerts therapeutic effects in pneumonia via cytokine signaling in the immune system, IL signaling, IL-4 and IL-13 signaling, and the immune system." (PMID 34306143, 2021). "Proinflammatory cytokines such as IFN-γ, IL-4, IL-17A, and IL-10 play important roles in the immunization process against S. pneumonia." (PMID 29375585, 2017). "Patients with severe pneumonia and high clinical pulmonary infection scores presented higher levels of IL-4 and IL-5 in serum than those with low scores (P < 0.01)." (PMID 24977240, 2014). "Also, patients with severe pneumonia had significantly higher serum levels of IL-4, IL-5, and IL-13 than those with mild pneumonia, indicative of the role of influenza virus infection in airway type 2 inflammation." (PMID 40083723, 2025). "However, our study suggests that elevated levels of IL-4 and INF-γ in BALF are closely associated with the development of MSLC, which often represents more severe pneumonia in children." (PMID 40406149, 2025). "The Feishu point efficacy system-pneumonia system network shows that cytokine signaling in the immune system, signaling by interleukins (ILs), IL-4 and IL-13 signaling, and the immune system may be related to immunity and inflammation." (PMID 34306143, 2021). "The Feishu point efficacy system had 4 pathways that could function in pneumonia, including cytokine signaling in the immune system, signaling by interleukins (ILs), IL-4 and IL-13 signaling, and the immune system." (PMID 34306143, 2021). "Also in pediatric patients with pneumonia, IL-4 was a reliable marker of severity of the disease." (PMID 30343359, 2018). "In animals with the acute pneumonia model, there was a decrease in the number of CD4+ FoxP3+ cells and a violation of the ratio of anti-inflammatory cytokines, including IL-4 and TGF-β." (PMID 41463029, 2025). "Seven hub genes, IL4, IL6, CSF2, IFNG, IL1B, TNF and IL17A, were responsible for Experimental Lung Inflammation, Pneumonitis, Pneumonia and Lobar Pneumonia." (PMID 36989283, 2023).
pneumonia (continued). "After 2 and 4 months, a delayed-type hypersensitivity (DTH) response, the degree of pneumonia-affected lung tissue, CFU, T cell count, and cytokine expression (IL-2, IL-4, IL-10, and IFN-γ) were determined." (PMID 35562916, 2022). "In addition, IL-2, IL-4, IL-6, IL-10, TNF-α, and IFN-γ levels were elevated by varying amounts depending on the type of pneumonia." (PMID 41011430, 2025). "Compared to pH1N1 patients without pneumonia, those who developed acute pneumonia due to pH1N1 exhibited significantly elevated levels of Th2 cytokines (IL-4, IL-5, and IL-13) in their serum." (PMID 40529241, 2025). "Here, we analyzed the levels of EOS, IgE, IL-4, IL-5 and INF-γ in children with pneumonia." (PMID 39764167, 2024). "This study found that serum IL-4 in the migraine group was higher than that in the pneumonia without headache group, but was not significantly different, as compared with the encephalitis group." (PMID 38356891, 2024). "As shown from the pneumonia samples, representative proinflammatory cytokines such as IL-6, IL-1β, IL-4, IFN-γ, and TNF-α were adsorbed to the DND irrespective of the disease type." (PMID 35445003, 2022). "The prediction capability of IL-4/IL-17A was greater than that of other commonly used indicators, including NLR (AUC = 0.897), oxygenation index (AUC = 0.795), CURB-65 (AUC = 0.795), and pneumonia severity index (PSI) (AUC = 0.786)." (PMID 34692846, 2021). "In addition, the levels of IL-4, IL-5, IL-13, and IL-17A in BALF were also significantly higher in the pneumonia group." (PMID 30723734, 2019). "But interestingly, consistent with their high CD4+/CD4- ratio, iNKT cells from patients who did not develop pneumonia presented a higher frequency of IL-4 positive cells." (PMID 31253189, 2019). "Our data showed that neonatal S. pneumoniae pneumonia can increase the infiltration of inflammatory cells, both in the lung tissues and in the BALF, along with releasing higher levels of the pro-inflammatory cytokines (IL-4, IL-5, IL-13, and IL-17A)." (PMID 30723734, 2019). "This increase in IL-4+ iNKT cells among patients who did not develop pneumonia is rather surprising." (PMID 31253189, 2019). "As for IL-4 in migraine group [3.52 (3.97) pg/mL], in encephalitis with headache group [2.99 (3.25) pg/mL], in pneumonia without headache group [2.44 (1.87) pg/mL], there were statistical differences in the overall distribution of IL-4 levels among the three groups (H = 12.81, p = 0.002)." (PMID 38356891, 2024). "The key findings were as follows: the serum levels of IL-4, TNF-α, IL-17A, and IL-12p70 were higher than those in the pneumonia without headache group, and the serum level of IL-12p70 was higher than that in the encephalitis with headache group." (PMID 38356891, 2024). "In comparison with non-treated control mice, treated animals with IDO blocker showed a non-significant decrease of pulmonary bacillary counts and lesser expression of IFN-γ, IL-4, TNF-α, and TGF-β, as well as lesser pneumonia, but these were non-significant." (PMID 37284503, 2023). "Compared with encephalitis with headache symptoms group and pneumonia without headache symptoms group the serum levels of IL-4, TNF-α, IL-17A, and IL-12p70 were higher in migraine group than in pneumonia group, and the levels of IL-12p70 were higher than those in encephalitis group (p < 0.05)." (PMID 38356891, 2024).
pancreatic cancer (42 papers, 2005 to 2025). "The aim of this review was to summarize the present knowledge about the IL-4/IL-13 cytokine-receptor system focusing on pancreatic cancer to help to develop attractive targets for novel diagnostic and therapeutic approaches for pancreatic cancer." (PMID 33804263, 2021). "We now report for the first time that IL-4 significantly enhanced the growth of five out of six cultured pancreatic cancer cell lines in a dose-dependent manner in association with an increased fraction of cells in S-phase." (PMID 15714203, 2005). "Interleukin-4 (IL4) was inversely associated with pancreatic cancer risk." (PMID 35064782, 2022). "The overexpressed IL-4/IL-13 cytokine-receptor system in cancers including pancreatic cancer may provide an attractive target for novel diagnostic and prognostic tools." (PMID 33804263, 2021). "The tumor-promoting properties of IL-4 have been substantiated through in vitro investigations in prostate and pancreatic cancer models, where elevated IL-4 levels correlate strongly with enhanced cell proliferation and progression." (PMID 40507238, 2025). "This approach augments NKG2D-CAR-T cell efficacy within the pancreatic tumor microenvironment, enhancing their activation, degranulation, cytokine production, and cytotoxicity against IL-4-expressing pancreatic cancer cells." (PMID 40612946, 2025). "IL-4 and IL-13 act on pancreatic cancer cells mainly through their receptor heterodimers IL-4-receptor-alpha (IL-4Rα) and IL-13Rα1, termed type II IL-4R, via signal pathways of STAT3/6, IRS-ERK/PI3K-Akt and mTOR." (PMID 35409019, 2022). "In our previous studies, the expression of IL-4 and IL-13 ligands, as well as IL-4Rα and IL-13Rα1 receptor chains, was shown in pancreatic cancer cell lines." (PMID 35409019, 2022). "Now, increasing evidence indicates salient activities of IL-4, IL-13 and their specific receptor complex IL-4Rα/IL-13Rα1 in carcinomas including pancreatic cancer." (PMID 35409019, 2022). "The related inflammatory cytokines IL-4 and IL-13 can regularly be detected at increased levels in the microenvironment of pancreatic cancer." (PMID 35409019, 2022). "Exogenous IL-4 and IL-13 enhanced the growth of pancreatic cancer cells, while IL-4-/IL-13-neutralizing antibodies counteracted this effect." (PMID 35409019, 2022). "Exogenous IL-4 and IL-13 enhanced the growth of pancreatic cancer cells in a dose-dependent manner, which was inhibited by IL-4-/IL-13-neutralizing antibodies." (PMID 35409019, 2022). "As expected, treatment of pancreatic cancer cells with IL-4-CM significantly (p < 0.001) increased their migratory and invasive capacity compared to VCM." (PMID 36333531, 2022). "The expression of IL-4 and IL-13, as well as IL-4Rα and IL-13Rα1 receptor chains, was shown in several cultured pancreatic cancer cell lines by us and by other research groups." (PMID 35409019, 2022). "Consistent with our findings, IL4+ basophils were found to reduce the survival of pancreatic cancer patients by regulating Th2 inflammation." (PMID 36058929, 2022). "Changes in the downstream signalling of the IL-4 and IL-13 axis in pancreatic cancer cells were investigated in Capan-1." (PMID 35409019, 2022). "In a mouse model of pancreatic cancer, basophils recruited to tumor draining lymph nodes were activated by T cell-derived IL-3 to produce IL-4, promoting Th2 cell and M2 macrophage differentiation which favors pancreatic cancer development." (PMID 35693800, 2022). "Increasing evidence supports the critical roles for IL-4 and IL-13 in the progression of pancreatic cancer." (PMID 33804263, 2021). "In an indirect coculture system, M2-polarized TAMs induced by IL-4-treatment enhanced the malignant phenotypes of pancreatic cancer cells, promoting epithelial–mesenchymal transition (EMT), and eventually leading to increased cell proliferation and migration." (PMID 33804263, 2021).
pancreatic cancer (continued). "It is important to understand the signaling pathways of IL-4 in pancreatic cancer as possible therapeutic targets." (PMID 33804263, 2021). "For example, previous work showed that exogenous human IL-4 (5 nM) enhanced the growth of COLO-357, and further studies confirmed that IL-4 exerted dose-dependent increases in the growth of four other cultured pancreatic cancer cell lines." (PMID 33804263, 2021). "Similar to the synergistic anti-tumor activity of IL-4 cytotoxin and gemcitabine, the combination of IL-13 cytotoxin with gemcitabine exhibited a remarkable and specific anti-tumor impact in pancreatic cancer cells and advanced pancreatic cancer animal models." (PMID 33804263, 2021). "Studies demonstrated that IL-4 exerts stimulating effects on pancreatic cancer cell proliferation and survival." (PMID 33804263, 2021). "Triple genetic modification enabled SmarT cells to specifically recognize PSCA-positive pancreatic cancer cells, expand, persist, and kill tumor cells in an immunosuppressive TGFβ and IL-4 rich environment." (PMID 30828333, 2019). "PSCA-CAR T cells initially killed PSCA-positive pancreatic cancer cells, but only PSCA.4/7-ICR-CAR T cells killed and expanded in the presence of both pancreatic cancer cells and the inhibitory cytokine IL-4." (PMID 30828333, 2019). "IL-4 mRNA has previously been shown to be downregulated in the liver of pancreatic cancer patients suffering from cachexia." (PMID 30513792, 2018). "In contrast, the endogenous activation of IL-4Rα in pancreatic cancer, either by auto- and paracrine IL-4 stimulation or by constitutive activation of IL-4Rα and its effects has not yet been examined." (PMID 28350325, 2017). "Combining our new results with former results by our group, an association between different expressions of receptor chains and different effects of IL-4 stimulation in pancreatic cancer can be suggested." (PMID 28350325, 2017). "Focusing on pancreatic cancer, exogenous IL-4 and IL-13 increased the growth of cultured cancer cells, possibly by stimulating growth-promoting pathways such as MAP-kinases." (PMID 28350325, 2017). "The present study indicates that endogenously expressed IL-4 and IL-4Rα contribute to the malignant phenotype of pancreatic cancer cells by activating diverse pro-oncogenic signaling pathways." (PMID 28350325, 2017). "Exogenous interleukin-4 (IL-4) has been demonstrated to affect the growth of different human malignancies including pancreatic cancer cells." (PMID 28350325, 2017). "Previously, IL-4-PE was shown to exert a synergistic effect with gemcitabine against the in vitro and in vivo pancreatic cancer models." (PMID 24868471, 2014). "Taken together, these findings suggest a potential involvement of IFN-γ (and IL-4) in the regulation of B7-H3 expression in pancreatic cancer." (PMID 20035626, 2009). "Our results demonstrate for the first time that pancreatic cancer cells produce IL-4 and that IL-4 can act as a growth factor in pancreatic cancer cells." (PMID 15714203, 2005). "Our present study not only demonstrated that IL-4 can exert growth stimulatory effects in pancreatic cancer cells but that they themselves express different amounts of IL-4." (PMID 15714203, 2005). "The aim of this study was to characterise the effects of IL-4 on the growth and signalling pathways of pancreatic cancer cells." (PMID 15714203, 2005). "The present study revealed for the first time that IL-4 also exerts proliferative effects in the majority of pancreatic cancer cell lines." (PMID 15714203, 2005). "Human IL-4 exerted a dose-dependent increase on the growth of five pancreatic cancer cell lines under serum-free conditions." (PMID 15714203, 2005). "Initially, we reviewed the clinical data of patients, conducted univariate analysis, and combined with literature research on prognostic factors of pancreatic cancer, finally including 11 biological indicators (IL-2, IL-4, IL-6, IL-17, IFN-γ, NLR, LDH, CEA, AFP, CA19-9, β2-MG)." (PMID 41384105, 2025).
pancreatic cancer (continued). "IL-4 and IL-13 are reported to promote pancreatic cancer progression via Type II IL-4 receptor signaling, which enhances tumor proliferation, invasion, and immune escape in pancreatic cancer." (PMID 41384105, 2025). "In addition, the activation of MAPK, PI3K-Akt, YAP-TAZ, and JAK-STAT3 signaling pathways by Kras in pancreatic cancer cells results in the upregulation of various suppressive cytokines and chemokines, such as IL-4, IL-6, IL-13, CSF1, and MCP-140,41." (PMID 37184030, 2023). "The aim of this review was to summarize knowledge about IL-4 and IL-13 and their receptors in pancreatic cancer in order understand the implication of IL-4 and IL-13 and their receptors for pancreatic tumorigenesis and progression and for developing possible new diagnostic and therapeutic targets." (PMID 33804263, 2021). "Another IL-4 cytotoxin, composed of IL-4 and truncated Pseudomonas exotoxin, exhibited specifical and efficient cytotoxicity to pancreatic cancer cells and when combined with gemcitabine showed synergistic anti-tumor activity in vitro and in metastatic and orthotopic mouse models." (PMID 33804263, 2021). "In addition, IL-4-blockade had a significantly inhibitory impact on pancreatic cancer progression, where IL-4 neutralizing antibody was proven to inhibit the basal growth of COLO-357, PANC-1, and MIA PaCa-2 cells." (PMID 33804263, 2021). "Effectiveness of this strategy was demonstrated against pancreatic cancer using a PSCA-specific CAR engineered with an inverted IL-4/IL-7 chimeric cytokine receptor (4/7-ICR), which contains an IL-4 extracellular domain fused to an activating IL-7 intracellular domain." (PMID 30828333, 2019). "Previous studies by our group have shown the presence and biological responsiveness of the IL-4-receptor in pancreatic cancer cells by growth inhibition induced by Pseudomonas exotoxin coupled to IL-4, as well as growth promotion by exogenous IL-4 in pancreatic cancer cells." (PMID 28350325, 2017). "Future projects may aim to determine further aspects of this pathway regarding IL-4 induced chemotherapy resistance and interactions with neighboring cells, especially focusing on pancreatic cancer stem cells." (PMID 28350325, 2017). "Furthermore, L-4F led to down-regulation of IL-17A and IL-4, suggesting that, in addition to its direct anti-inflammatory effect, L-4F can change the phenotypes of TAMs in pancreatic tumors by altering the microenvironment." (PMID 29245934, 2017). "Therefore, we investigated the potential effects of the Th1 cytokine IFN-γ and Th2 cytokine IL-4 on the expression of B7-H3 on cultured pancreatic cancer cells." (PMID 20035626, 2009). "First, IL-4 stimulated growth of five pancreatic cancer cell lines." (PMID 15714203, 2005). "Together with the observation that pancreatic cancer cells express high levels of IL-4Rs, our results raise the possibility that IL-4 may have a dual effect in human pancreatic cancers." (PMID 15714203, 2005). "Studies have shown that IL-4 has a stimulatory effect on proliferation and survival in pancreatic cancer cells acting as an autocrine growth factor, and cancer-derived IL-4 may also inhibit cancer-directed immune surveillance in vivo, thereby promoting pancreatic tumor growth and metastasis." (PMID 40259042, 2025). "Consequently, increased levels of protein and mRNA of the IL-4/IL-13-receptor axis may be useful biomarkers for disease activity and prognosis in patients with pancreatic cancer." (PMID 33804263, 2021).